VAC14 (VAC14 component of PIKFYVE complex)
Description:
Scaffold protein component of the PI(3,5)P2 regulatory complex which regulates both the synthesis and turnover of phosphatidylinositol 3,5-bisphosphate (PtdIns(3,5)P2). Pentamerizes into a star-shaped structure and nucleates the assembly of the complex. The pentamer binds a single copy each of PIKFYVE and FIG4 and coordinates both PIKfyve kinase activity and FIG4 phosphatase activity, being required to maintain normal levels of phosphatidylinositol 3-phosphate (PtdIns(3)P) and phosphatidylinositol 5-phosphate (PtdIns(5)P). Plays a role in the biogenesis of endosome carrier vesicles (ECV) / multivesicular bodies (MVB) transport intermediates from early endosomes.
Synonyms: TAX1BP2; TRX; FLJ10305; ArPIKfyve
Tractability: Antibody: UniProt places it where antibodies can reach, with high confidence. PROTAC: ubiquitination databases record sites on it; its protein half-life has been measured.
Safety:
Unwanted effects reported when the protein is acted on. In parentheses: how it was acted on, where the effect was seen, and who reports it.
neuropathy (source: ClinPGx)
Gene: Protein-coding gene on chromosome 16 (70,687,439 to 70,801,173, reverse strand). Ensembl gene ENSG00000103043.
Subcellular location: Endosome membrane; Microsome membrane
Subcellular location (Human Protein Atlas): Vesicles; Cytosol
Pathways (Reactome):
Metabolism: Synthesis of PIPs at the Golgi membrane; Synthesis of PIPs at the early endosome membrane; Synthesis of PIPs at the late endosome membrane
Gene Ontology:
Molecular function: identical protein binding; protein binding; signaling receptor activity
Biological process: 1-phosphatidyl-1D-myo-inositol 3,5-bisphosphate metabolic process; phosphatidylinositol biosynthetic process; signal transduction; regulation of postsynaptic neurotransmitter receptor internalization
Cellular component: endosome membrane; PAS complex; early endosome membrane; Golgi membrane; late endosome membrane; endosome; presynaptic endosome
Genetic constraint (gnomAD): Loss-of-function variants: 44 observed, 83.02 expected, observed/expected ratio (o/e) 0.53, 90% interval 0.41 to 0.68. The upper end of that interval is the gene's LOEUF score, 0.68, which puts it in group 2 of 6, group 1 being the genes least tolerant of losing a copy. Missense variants: 790 observed, 961.2 expected, observed/expected ratio (o/e) 0.82, 90% interval 0.77 to 0.87. Synonymous variants: 417 observed, 411.98 expected, observed/expected ratio (o/e) 1.01, 90% interval 0.93 to 1.1.
Homologues: Orthologues: chimpanzee VAC14 (99% identical), macaque VAC14 (99% identical), dog VAC14 (96% identical), pig VAC14 (95% identical), rat Vac14 (95% identical), mouse Vac14 (94% identical), rabbit VAC14 (94% identical), guinea pig VAC14 (94% identical), zebrafish vac14 (81% identical), tropical clawed frog vac14 (81% identical), Drosophila melanogaster CG5608 (43% identical), Caenorhabditis elegans vacl-14 (34% identical).
Diseases named in the same sentence as VAC14 in open-access papers:
VAC14 is named in the same sentence as 28 diseases in open-access papers, as found by Europe PMC text mining. Sharing a sentence is not in itself a finding about the gene and the disease. The quoted sentences say what the papers report.
Alzheimer disease (5 papers, 2016 to 2022). A progressive, neurodegenerative disease characterized by loss of function and death of nerve cells in several areas of the brain leading to loss of cognitive function such as memory and language. "In addition, one computational analysis associated a Vac14 variant with Alzheimer’s disease and bipolar disorder." (PMID 36493904, 2022). "Here we show that the Amyloid Precursor Protein (APP), a central molecule in Alzheimer’s disease, associates with the PIKfyve complex (consisting of Vac14, PIKfyve and Fig4) and that the APP intracellular domain directly binds purified Vac14." (PMID 26216398, 2016). "Our recent work has shown that the intracellular domain of the amyloid precursor protein (APP), a molecule central to the aetiology of Alzheimer's disease binds to VAC14 and enhances PIKfyve function." (PMID 26934981, 2016). "In addition, Vac14 physically interacts with amyloid precursor protein (APP), the central player in Alzheimer's disease, and synphilin-1, an aggregation-prone protein implicated in Parkinson's disease." (PMID 36493904, 2022). "However, our recent work has shown that the amyloid precursor protein (APP), a central molecule in Alzheimer's disease, binds to the VAC14 scaffold of the complex and enhances the activity of the PIKfyve complex in cells, providing a specific activator of this important enzyme complex." (PMID 26934981, 2016).
amyotrophic lateral sclerosis (5 papers, 2016 to 2025). Amyotrophic lateral sclerosis (ALS) is a neurodegenerative disease characterized by progressive muscular paralysis reflecting degeneration of motor neurons in the primary motor cortex, corticospinal tracts, brainstem and spinal cord. "Furthermore, as with TRPML1, mutations in the human PIKfyve complex, namely the FIG4 and Vac14 components, lead to neurodegeneration – in this case, including amyotrophic lateral sclerosis (ALS), Charcot–Marie–Tooth disease, and Yunis–Varon syndrome." (PMID 36825945, 2023). "Finally, the significance of this complex is highlighted in humans where loss-of-function mutations in FIG4 and VAC14 genes result in severe neurological disorders including Amyotrophic Lateral Sclerosis (ALS), Charcot Marie Tooth Type 4 J and Yunis-Varón Syndrome13,15–18." (PMID 41315403, 2025).
bacteremia (1 paper, 2022). "Among the 9 sites, 2 CpG sites were distributed in VAC14, which is relevant to bacteremia secondary to multiple pathogens." (PMID 35242787, 2022).
Charcot-Marie-Tooth disease type 4J disease (1 paper, 2013). "This suggests that the neurodegenerative phenotype observed in mice deficient in Fig4 or Vac14, and in Charcot-Marie-Tooth disease type 4J disease in humans, is unlikely to be mediated by apoptosis." (PMID 23544129, 2013).
Hydrocephalus (1 paper, 2011). Hydrocephalus is an active distension of the ventricular system of the brain resulting from inadequate passage of CSF from its point of production within the cerebral ventricles to its point of absorption into the systemic circulation. "The hydrocephalus in these mice is very similar to that in the L156R (ingls) mutant of Vac14." (PMID 21655088, 2011).
Parkinsonism (1 paper, 2024). Characteristic neurologic anomaly resulting from degeneration of dopamine-generating cells in the substantia nigra, a region of the midbrain, characterized clinically by shaking, rigidity, slowness of movement and difficulty with walking and gait. "Two significant gene clusters (clusters 7 and 73) included genes previously associated with Parkinsonism (FIG4 and VAC14) and IBD (IFNAR1, IL6ST, ATG16L1, and NOD2)." (PMID 38741190, 2024).
periodontitis (1 paper, 2024). An acute or chronic inflammatory process that affects the tissues that surround and support the teeth. "MR analysis corroborated the inferences drawn from scRNA-seq, identifying ten causal gene markers associated with periodontitis, including LIMA1, PEA15, TMEM158, CMTM6, PDP1, FFAR4, VAC14, and ENHO." (PMID 39830509, 2024).
prion disease (1 paper, 2021). A transmissible disease that is caused by a protein that is able to induce abnormal folding of normal cellular proteins, leading to characteristic spongiform brain changes, which are associated with neuronal loss without an inflammatory response. "While VAC14 and FIG4 levels were not affected at any time point during the progression of prion disease, co‐immunoprecipitation experiments revealed that VAC14 lost its association with FIG4 and PIKfyve in prion‐infected brains at the terminal stage of the disease." (PMID 34291577, 2021).
Yunis-Varón syndrome (1 paper, 2023). "The lethal multisystem disorder Yunis-Varón Syndrome results from complete loss-of-function of FIG4 or VAC14." (PMID 37363915, 2023). "Reduction of CLCN7 provides a new target for treatment of FIG4 and VAC14 deficiencies that lack specific therapies, such as Charcot-Marie-Tooth Type 4J and Yunis-Varón syndrome." (PMID 37363915, 2023).
Neurological Disease (4 papers, 2009 to 2025). "Published studies revealed that VAC14 ingls and FIG4 pale tremor mice had lightening of the coat and severe neurologic disease, resulting in early lethality and the accumulation of autophagosomes within the CNS." (PMID 29584722, 2018).
neurodegenerative disease (2 papers, 2011 to 2025). A disorder of the central nervous system characterized by gradual and progressive loss of neural tissue and neurologic function. "This mechanistic framework may explain the paradoxical therapeutic effects of acute PIKfyve inhibition in neurodegenerative disease models, despite the pathological consequences of genetic PIKfyve/Fig4/Vac14 dysfunction." (PMID 41315403, 2025). "In another example of the importance of interactions between proteins in this complex, the missense mutation of Vac14 in the ingls mouse which reduces the affinity of VAC14 for FAB1 and results in a neurodegenerative disease that closely resembles the Fig4 null mice." (PMID 21655088, 2011).
peripheral neuropathy (2 papers, 2019 to 2023). A disorder affecting the peripheral nervous system. "A recent GWAS of docetaxel-induced peripheral neuropathy identified a gene implicated in neurodegeneration (VAC14), and a gene related to cellular structure (CEP72) was identified in a GWAS for vincristine-induced neurotoxicity." (PMID 30909387, 2019).
VAC14 also shares sentences with these, for which no sentence is quoted: bipolar disorder (3 papers); cancer (2); brain diseases (1); cervical cancer (1); cognitive decline (1); diabetes mellitus (1); lung carcinoma (1); lysosomal disorders (1); malignant melanoma (1); mental disorder (1); neuropathy (1); polyneuropathy (1); Sepsis (1); type 1 diabetes (1); Type 2 diabetes (1); viral infection (1).